POU3F1 (POU class 3 homeobox 1)
Description:
Transcription factor that binds to the octamer motif (5'-ATTTGCAT-3') (By similarity). Acts as a transcriptional activator when binding cooperatively with SOX4, SOX11, or SOX12 to gene promoters (By similarity). Acts as a transcriptional repressor of myelin-specific genes (By similarity).
Synonyms: OCT6; OTF6; SCIP
Tractability: PROTAC: ubiquitination databases record sites on it.
Gene: Protein-coding gene on chromosome 1 (38,043,829 to 38,046,793, reverse strand). Ensembl gene ENSG00000185668.
Subcellular location: Nucleus
Subcellular location (Human Protein Atlas): Nucleoplasm
Pathways (Reactome):
Developmental Biology: EGR2 and SOX10-mediated initiation of Schwann cell myelination; Formation of the anterior neural plate; Formation of the posterior neural plate
Gene Ontology:
Molecular function: sequence-specific DNA binding; sequence-specific double-stranded DNA binding; DNA-binding transcription factor activity; DNA-binding transcription factor activity, RNA polymerase II-specific; RNA polymerase II cis-regulatory region sequence-specific DNA binding; DNA binding
Biological process: axon ensheathment; positive regulation of DNA-templated transcription; positive regulation of gene expression; regulation of transcription by RNA polymerase II; brain development; regulation of DNA-templated transcription
Cellular component: nucleoplasm; chromatin; nucleus; RNA polymerase II transcription regulator complex; transcription regulator complex
Genetic constraint (gnomAD): Loss-of-function variants: 4 observed, 9.02 expected, observed/expected ratio (o/e) 0.44, 90% interval 0.22 to 1.01. That is too few expected variants to judge how well the gene tolerates losing a copy. Missense variants: 505 observed, 490.9 expected, observed/expected ratio (o/e) 1.03, 90% interval 0.96 to 1.11. Synonymous variants: 354 observed, 260.41 expected, observed/expected ratio (o/e) 1.36, 90% interval 1.25 to 1.48.
Homologues: Orthologues: chimpanzee POU3F1 (100% identical), macaque POU3F1 (99% identical), dog POU3F1 (99% identical), pig POU3F1 (99% identical), rat Pou3f1 (99% identical), mouse Pou3f1 (99% identical), guinea pig POU3F1 (61% identical), zebrafish pou3f1 (55% identical), tropical clawed frog pou3f1 (55% identical), Drosophila melanogaster vvl (42% identical), zebrafish pou5f3 (27% identical), Caenorhabditis elegans ceh-18 (22% identical), and 2 more. Paralogues in human: POU3F3 (51% identical), POU3F2 (48% identical), POU3F4 (43% identical), POU2F1 (30% identical), POU5F1 (28% identical), POU2F2 (27% identical), POU2F3 (27% identical), POU5F1B (27% identical), POU1F1 (23% identical), POU4F2 (22% identical), POU4F3 (22% identical), POU4F1 (22% identical), and 5 more.
Diseases named in the same sentence as POU3F1 in open-access papers:
POU3F1 is named in the same sentence as 30 diseases in open-access papers, as found by Europe PMC text mining. Sharing a sentence is not in itself a finding about the gene and the disease. The quoted sentences say what the papers report.
colorectal cancer (2 papers, 2022 to 2024). A primary or metastatic malignant neoplasm that affects the colon or rectum. "In ulcerative colitis-associated colorectal cancer, NFATc3 regulates macrophage inflammation and carcinogenesis, mediated by Pou3f1." (PMID 39822413, 2024). "Pou3f1 facilitates NFATc3 in ulcerative colitis-associated colorectal cancer development." (PMID 39822413, 2024). "Thus, the results suggested that Pou3f1 promoted inflammation and inflammatory cell infiltration in colitis-associated colorectal cancer." (PMID 36064319, 2022). "It indicated that Pou3f1 might drive the development of colitis-associated colorectal cancer." (PMID 36064319, 2022).
bipolar disorder (1 paper, 2010). A disorder of the brain that causes unusual shifts in mood, energy, activity levels and the ability to carry out day-to-day tasks. "POU3F1 was also proved to affect calcium flux through binding to the promoter region of PIK3C3 (MIM 602609), a member of the phosphatidylinositide 3-kinase family, and mutations in PIK3C3 have been shown to be involved in a subset bipolar disorder and schizophrenia patients." (PMID 20808825, 2010).
bladder cancer (1 paper, 2015). "For example, in bladder cancer (BLCA) we have provided a list of 65, 208, and 65 genes that may be regulated by POU3F1, FOXA1, or CEBPA, respectively, by binding to a specific hypomethylated enhancer." (PMID 25994056, 2015).
colon tumors (1 paper, 2022). "Knockdown of Pou3f1 suppressed cell proliferation and increased cell death in colon tumors." (PMID 36064319, 2022).
deafness (1 paper, 2023). An inherited or acquired condition characterized by the complete loss of the ability to hear from one or both ears. "In mammals, Pou3f1 appears to be the key factor for neural fate promotion, while the only neural defect caused by the loss of Pou3f4 is deafness." (PMID 36831281, 2023).
epilepsy (1 paper, 2021). A brain disorder characterized by episodes of abnormally increased neuronal discharge resulting in transient episodes of sensory or motor neurological dysfunction, or psychic dysfunction. "Herein, we identified seven genes (NCL, SEPHS2, PA2G4, SLC35G2, MYO1C, GPR158, and POU3F1) with de novo variants but unknown pathogenicity that were not previously associated with epilepsy." (PMID 34489640, 2021).
Ewing sarcoma (1 paper, 2025). A small round cell tumor that lacks morphologic, immunohistochemical, and electron microscopic evidence of neuroectodermal differentiation. "Among our 12 MTF candidates, only POU3F1 and POU3F2 were reported as dependencies in Ewing sarcoma (among 28 TFs, 291 genes, Supp." (PMID 41444391, 2025). "Data 5), we selected six MTFs (TCF12, SOX6, POU3F1, POU3F2, NKX2-2, and IKZF2) as putative members of the Ewing sarcoma CRC, based on fulfilling at least two out of these three criteria." (PMID 41444391, 2025).
infertile (1 paper, 2017). "DMRTB1 was a down-regulated common gene among MArrest, oligospermia and Ikbkap KO, GPR137B was common among teratospermia, Bcl6b and Pou3f1 KD, and LMNB2 was common among Bcl6b, Etv5 and Pou3f1 KD infertile mice." (PMID 29150651, 2017). "We compared nine types of infertility in male humans and mice, including MArrest, oligospermia and teratospermia in humans and Ing2 Knockout (KO), Bcl6 KD, Etv5 KD, Pou3f1 KD, Ikbkap KO and Dazap1 mutant in mice." (PMID 29150651, 2017).
male infertility (1 paper, 2017). The inability of the male to effect fertilization of an ovum after a specified period of unprotected intercourse. "In human and mouse male infertility, we observed the highest similarity between Etv5 and Pou3f1 KD in the up-regulated gene lists." (PMID 29150651, 2017).
rheumatoid arthritis (1 paper, 2025). A chronic, systemic autoimmune disorder characterized by inflammation in the synovial membranes and articular surfaces. "(C) POU3F1 eQTL that became significantly colocalized with rheumatoid arthritis (RA) association by meta-analyzing LCL eQTL data." (PMID 41396161, 2025).
teratospermia (1 paper, 2017). "The higher number of common up-regulated genes was found between Etv5 KD and Pou3f1 KD, with 53 genes, Bcl6b KD and Etv5 KD, with 19 genes, Bcl6b KD and Pou3f1 KD, with 14 genes, MArrest and teratospermia, with 12 genes, and MArrest and Ing2 KO, with nine common genes." (PMID 29150651, 2017).
tumor (3 papers, 2016 to 2025). "qPCR analysis of tumours from each group revealed that Pknox2, Irf4, Pou3f1, Cebpb, and Meox1 were significantly upregulated by propionate and B. fragilis." (PMID 40715695, 2025). "Our study showed that knockdown of Pou3f1 abrogated inflammatory mediator secretion in macrophages, resulting in the inhibition of tumor growth in UC-CRC." (PMID 36064319, 2022). "The total tumor number and the number of tumors with different sizes were reduced by Pou3f1 inhibition." (PMID 36064319, 2022). "Strikingly, when integrating the transcriptome under HO-1 modulation with the HO-1 interactome, a framework of four main molecular pathways arose as the foundation for the regulation of the tumor cell protrusive forces: ANXA2/HMGA1/POU3F1; NFRSF13/GSN; TMOD3/RAI14/VWF; PLAT/PLAU." (PMID 28032857, 2016). "The integration from our omics-based research provides a four molecular pathway foundation (ANXA2/HMGA1/POU3F1; NFRSF13/GSN; TMOD3/RAI14/VWF; and PLAT/PLAU) behind HO-1 regulation of tumor cytoskeletal cell compartments." (PMID 28032857, 2016).
infection (1 paper, 2022). The state of being infected such as from the introduction of a foreign agent such as serum, vaccine, antigenic substance or organism. "Thus, the adenovirus carrying the interference sequence of Pou3f1 (Ad-shPou3f1) was used to infect RAW264.7 cells, and the infection efficiency was confirmed." (PMID 36064319, 2022).
POU3F1 also shares sentences with these, for which no sentence is quoted: depression (2 papers); ulcerative colitis (2); cancer (1); colitis (1); esophageal adenocarcinoma (1); Huntington disease (1); Intellectual disability (1); liver cancer (1); microcephaly (1); microtia (1); neurofibroma (1); non-small cell lung carcinoma (1); Obesity (1); oligospermia (1); Pectus carinatum (1); progressive multifocal leukoencephalopathy (1); schizophrenia (1).